INS (insulin)
Diseases named in the same sentence as INS in open-access papers (continued):
Sharing a sentence is not in itself a finding about the gene and the disease.
Hyperglycemia (continued). "During insulin-resistance states such as T2D, the control of hepatic glucose production by insulin is defective yet the lipid promoting effects of insulin are maintained, leading to hyperglycemia and hypertriglyceridemia." (PMID 39057708, 2024). "Alternatively, prompt insulin interruption and checking for overt hyperglycemia or relapse in clinical signs in the following days would also be indicated." (PMID 38539988, 2024). "In these studies, we showed that Swiss female mice fed a HF/HS diet exhibit obesity, hyperglycemia, hypercholesterolemia, and reduced insulin sensitivity." (PMID 38585221, 2024). "In traits of hyperglycemia, the levels of fasting glucose (beta = 0.081 [0.026,0.135], P = 3.53×10−3) and fasting insulin (beta = 0.163 [0.082,0.244], P = 8.14×10−5) increased per 1-SD increase in ALT." (PMID 38662679, 2024). "Radish seeds significantly decrease hyperglycemia by reducing insulin resistance, limiting intestinal glucose absorption, and increasing glucose uptake in skeletal muscles." (PMID 39519546, 2024). "Our goal was to assess the expression of NFκB p65 and its negative regulator, Nrf2, in myenteric neurons and adjacent smooth muscle of different gut segments after chronic hyperglycaemia and immediate insulin treatment." (PMID 39457659, 2024). "It appears from the Chi-square analysis that all the children were in a situation of hyperglycemia and 93.3% of them were on insulin treatment." (PMID 38738016, 2024). "In gestational diabetes, β cells inadequately compensate for the increased demands of pregnancy, and when coupled with heightened insulin resistance, this leads to hyperglycemia." (PMID 39597780, 2024). "Pathologically, the decline of β-cell function and insulin action induces hyposensitivity, which exacerbates lipid disorders, hyperglycemia, and abnormal fibrinolysis." (PMID 37289375, 2024). "T1D is characterized by inadequate endogenous insulin production, resulting in persistent hyperglycemia (i.e., high blood glucose/sugar levels) and necessitating lifelong exogenous insulin administration to counter this effect." (PMID 38846748, 2024). "In first-onset, antipsychotic-naive patients with SZ, systemic glucose metabolism anomalies can lead to hyperglycemia, decreased glucose tolerance, and increased resistance to insulin." (PMID 38792361, 2024). "As a result of incretins’ ability to increase insulin production from pancreatic β cells following eating, blood insulin levels were lowered, and postprandial hyperglycemia was subsequently enhanced when bacterial DPP-4 restricted the proteolysis of incretins." (PMID 38337597, 2024). "Younger mice exposed to a prolonged high-fat diet and hyperglycemia showed increased insulin, glucose, and frequency of activated microglia in the dentate gyrus of the hippocampal formation and cornu ammonis of the hippocampus." (PMID 38550920, 2024). "The combination of hyperglycemia and dyslipidemia accelerates β-cell death, further reducing insulin secretion and exacerbating hyperglycemia." (PMID 39376657, 2024). "Although insulin is often the treatment of choice, mild hyperglycaemia (HbA1c < 8%) can be treated with metformin, which has also been recommended." (PMID 38255387, 2024). "The use of low-dose insulin can be considered due to its anabolic effects if needed to treat recalcitrant hyperglycemia." (PMID 39698355, 2024). "Diabetes is characterized by hyperglycemia, which results from issues with insulin production and/or sensitivity." (PMID 38613048, 2024). "This is a complex mechanism that occurs at the cellular level due to factors such as blood vessels, inflammation, and hyperglycemia and insulin resistance." (PMID 39720256, 2024). "In the pre-diabetic condition, insulin levels increase to compensate for insulin requirements, leading to chronic hyperinsulinemia, hyperglycemia-induced β-cell failure, and eventually T2DM." (PMID 39610878, 2024).
Hyperglycemia (continued). "In studies with silibinin, it has been reported that it increases the activity of pancreatic beta cells and insulin sensitivity and has a hyperglycemia‐reducing effect." (PMID 38726421, 2024). "In Type 2 diabetes (T2D), hyperglycemia arises from insulin resistance with an inadequate compensatory insulin secretory response." (PMID 38985787, 2024). "The authors concluded that STZ-treated rats, often used as a study model of T1DM, are characterized not only by decreased insulin levels and hyperglycemia, but also by hypoleptinemia." (PMID 39337082, 2024). "A previous study showed that Ogg1-KO mice fed a normal diet ad libitum exhibited hyperglycemia, elevated insulin levels, higher liver glycogen content, and inefficient suppression of gluconeogenesis." (PMID 39596235, 2024). "PI3K inhibitors used in cancer treatment often induce hyperglycemia, triggering insulin feedback mechanisms that diminish their efficacy in treating cancer." (PMID 38755637, 2024). "In the current study, diabetic rats showed significantly lower serum testosterone levels, likely due to reduced insulin stimulation of Leydig cells and hyperglycemia-induced oxidative damage to these cells." (PMID 39391856, 2024). "mTOR inhibitors‐induced hyperglycemia is mediated by the development of IR and impairment of insulin secretion." (PMID 39676616, 2024). "The prevailing treatment for T1DM involves daily subcutaneous insulin injections, but a substantial proportion of patients face challenges such as severe hypoglycemic episodes and poorly controlled hyperglycemia." (PMID 38884159, 2024). "DM is a metabolic disease that is primarily characterized by hyperglycemia resulting from the insufficient release of insulin, a defect in insulin action, or both." (PMID 39063010, 2024). "Our findings are consistent that h-GI meals require an additional dose of insulin to reduce postprandial hyperglycemia." (PMID 38257156, 2024). "Pre-EN blood glucose, hyperglycaemia during EN treatment, HbA1c, insulin use, oral route recovery, length of stay (LOS) and mortality at 30 days were collected." (PMID 38816400, 2024). "The use of intensive insulin therapy to control BG levels has been widely adopted for stress hyperglycemia in the last decade." (PMID 39009963, 2024). "The primary mechanism of GLP-1 analogs involves increasing insulin synthesis in response to hyperglycemia, reducing glucagon secretion in both hyperglycemic and euglycemic states, and slowing gastric emptying." (PMID 39518431, 2024). "It has been suggested that a reduced expression of miR-592 in the livers of obese humans and mice contributes to hyperglycemia and decreased sensitivity to insulin." (PMID 39595541, 2024). "The mechanism by which GCs induce hyperglycemia is thought to be by affecting the pancreatic beta cell and decreasing insulin synthesis, increasing insulin resistance, stimulating gluconeogenesis and lipolysis, and enhancing counter-regulatory hormones." (PMID 38867099, 2024). "In the present study, we showed that mogrol activated TGR5 and insulin release from pancreatic β-cells, alleviating hyperglycemia at least partly in diabetic KKAy mice." (PMID 38332164, 2024). "Bursicon, through its receptor Rickets, a Leucine-rich-repeat-containing G-protein coupled receptor (LGR), improves insulin secretion and insulin sensitivity in adipose tissue, mitigating hyperglycemia." (PMID 39033139, 2024). "A recent study found that, in individuals with severe COVID-19, inadequate insulin secretion in the face of increased insulin resistance (lower disposition index) was responsible for hyperglycemia during the acute phase." (PMID 37934800, 2024). "This impaired response to insulin exacerbates hyperglycemia through processes such as increased glycogenolysis and hepatic gluconeogenesis." (PMID 39683465, 2024). "During GDM, β-cells are unable to compensate for the demands of pregnancy and insulin sensitivity is reduced, leading to hyperglycemia." (PMID 38674907, 2024).
Hyperglycemia (continued). "One of the most common issues is neonatal hypoglycemia, which occurs due to increased fetal insulin production in response to maternal hyperglycemia." (PMID 39463673, 2024). "It was found that higher levels of ACAG had a significant correlation to hyperglycemia, insulin, HOMA-IR, HbA1c, total cholesterol, triglycerides, CRP, urine albumin/creatinine and eGFR at baseline (all P<0.05)." (PMID 39574951, 2024). "Mice with complete deletion of hepatic IRS2 develop hyperglycemia, impaired hepatic insulin signaling, and elevated gluconeogenesis." (PMID 38596462, 2024). "They focused on educating the patient in the area of practical skills, i.e., measuring glucose levels and administering insulin or glucagon, as well as dealing with hypo and hyperglycemia." (PMID 38486206, 2024). "Another study indicated that pharmacological activation of AMPK in insulin-resistant rats enhances the management of hyperglycemia, dyslipidemia, and hypertension." (PMID 39885962, 2024). "Significant improvements on insulin sensitivity, glucose intolerance, and hepatic glucose production as well as fasting hyperglycemia were observed after 10 weeks post AAV8-RIMKLA injection." (PMID 39117631, 2024). "Prunella vulgaris can improve impaired insulin secretion, vascular dysfunction, and metabolic abnormalities and markedly attenuate hyperglycaemia and vascular inflammatory processes in db/db T2DM mice." (PMID 38675115, 2024). "In addition, further studies should be aimed at assessing other metabolic variables, such as free fatty acids and triglycerides, and investigate whether metabolic changes caused by hyperglycemia are preventable with insulin treatment, after a normalized glycemic level is achieved." (PMID 38794147, 2024). "These treatments act to increase insulin sensitivity or availability and thus indirectly reduce hyperglycemia." (PMID 39597869, 2024). "Addition of dapagliflozin to alpelisib suppressed alpelisib-induced hyperglycemia and slightly reduced insulin levels." (PMID 39177931, 2024). "As evidenced in prior research, the transient hyperglycemia caused by PI3K inhibition often remains within a few hours, as insulin feedback mechanisms kick in to restore normal glucose homeostasis." (PMID 38755637, 2024). "Nonetheless, Alpha-2 adrenergic receptor agonists have been found to inhibit insulin release, stimulate glucagon release, or both from α and β cells, leading to hyperglycemia." (PMID 38791631, 2024). "Type 1 diabetes (T1D) is an autoimmune disease characterized by insulin-secreting β cell destruction by CD4+ and CD8+ T cells, resulting in insulin deficiency and hyperglycemia." (PMID 38464515, 2024). "Exogenous insulin therapy aims to maintain euglycemia, thereby potentially mitigating the harmful effects of hyperglycemia, such as inflammation, immune dysfunction, and tumor promotion." (PMID 39595655, 2024). "Accelerated high-fat-diet-induced hyperglycemia and glucose-induced decrease in plasma insulin levels in female mice.Slight increase in male islet area.Abnormal changes in endocrine and metabolic pathways in female pancreatic islets." (PMID 38251002, 2024). "Insulin sensitive tissues such as the liver and skeletal muscle are naturally the most affected from insulin insufficiency and hyperglycemia." (PMID 39377070, 2024). "This study evaluated the safety and efficacy of two insulin regimens for inpatient hyperglycemia management: combination short-plus long-acting insulin (basal-bolus insulin regimen, BBIR) vs. short-acting insulin only (correctional insulin only regimen, CIOR)." (PMID 38919469, 2024). "In trauma, persistent hyperglycemia intensifies ROS production, particularly within mitochondria, disrupting insulin signaling pathways." (PMID 39682557, 2024). "Insulin infusion remains the preferred method to control stress hyperglycemia in critically ill patients." (PMID 38698018, 2024).
Hyperglycemia (continued). "Early glargine administration in pediatric DKA management is safe, decreases the rate of rebound hyperglycemia, and improves the transition to subcutaneous insulin." (PMID 39136541, 2024). "In the insulin-resistant state, hyperglycemia facilitates intra to extracellular fluid dynamics, which raises blood pressure and plasma volume." (PMID 39768947, 2024). "Due to the use of insulin or hypoglycemic drugs, diabetic patients rarely die of hyperglycemia; on the contrary, 75% of diabetic patients die directly from cardiovascular disease." (PMID 39095691, 2024). "These molecules overrule the normal glycemic control mediated by insulin, inhibit glycogen synthesis and promote gluconeogenesis, resulting in stress-related hyperglycemia." (PMID 39107476, 2024). "The glycogen deposits built in the hepatocytes of these patients result during episodes of persistent hyperglycemia, where glucose gets converted to glycogen independently of insulin, which mediates the conversion of glucose to glycogen in the liver." (PMID 39156415, 2024). "It is characterized by hyperglycaemia due to an insufficient insulin response to compensate for the insulin-resistant state of pregnancy, a well-defined physiological response necessary to provide sufficient glucose for maternal and foetal requirements." (PMID 38334487, 2024). "The most recent consensus recommends the use of insulin for treating hyperglycemia post-transplantation surgery." (PMID 38559691, 2024). "The goal of insulin therapy is to mimic physiological insulin secretion, maintain blood glucose levels within a target range, and prevent both hyperglycemia and hypoglycemia." (PMID 39310514, 2024). "WD-induced hyperglycemia was accompanied by elevated plasma insulin concentrations, both in fed and in fasting conditions." (PMID 38550379, 2024). "In the case of intense EXE, post-EXE hyperglycaemia can be worsened due to the inability to increase insulin release and distribute it into the portal." (PMID 38542818, 2024). "Beyond the direct effects on insulin and glucose, exercise serves as a mitigating force against the deleterious consequences of long-term hyperglycemia." (PMID 38900771, 2024). "The unique insulin-producing cells suffer from the detrimental impact of glucotoxicity as induced by hyperglycemia, lipotoxicity as mediated by hyper- and dyslipidemia as well as ectopic fat storage, and a chronic inflammatory state." (PMID 38377787, 2024). "One week after the administration of antenatal corticosteroids, hyperglycemia persisted in 20 (35.71%) of the 56 participants in group 1, of which six (30%) participants required insulin therapy." (PMID 38854292, 2024). "We found that middle-aged and old Ghsr-βKO mice were protected from STZ-induced hyperglycemia and impaired insulin secretion, correlated with increased expression of insulin signaling regulators but decreased pro-inflammatory cytokines in pancreatic islets." (PMID 38794702, 2024). "Glucose-to-insulin ratios were also 84% lower (p < 0.05) during hyperglycemia than under basal conditions." (PMID 38535316, 2024). "We show that diabetic Goto‐Kakizaki (GK) rats exhibited impaired insulin secretion and hyperglycemia, along with decreased SNAP25 expression and ChREBP phosphorylation in islets." (PMID 39300600, 2024). "Conversely, stimulated ISR was higher in the non-NGT group during both OGTT and IIGI, which agrees with relative hyperglycemia and the characteristic hyperinsulinemia of insulin-resistant states." (PMID 38713514, 2024). "It is distinguished by hyperglycemia due to insufficient insulin production and/or insulin resistance." (PMID 39391856, 2024). "Over several years, it proceeds to necrosis of beta cells, a sharp drop in insulin levels, and hyperglycemia." (PMID 38837635, 2024). "In this regard, beta cell loss increases the burden on remaining beta cells to secrete more insulin to cope with hyperglycemia, which induces endoplasmic reticulum (ER) stress." (PMID 38844555, 2024).
Hyperglycemia (continued). "After 8 weeks of treatment, the administration of EPE to db/db mice effectively controlled hyperglycemia and hyperinsulinemia by markedly lowering blood glucose, insulin, and glycosylated HbA1c levels." (PMID 38928391, 2024). "Multiple investigations have demonstrated that anesthetics inhibit insulin secretion by obstructing ATP-sensitive K + channels in β-cells, resulting in elevated blood sugar levels (hyperglycemia)." (PMID 38926827, 2024). "The study included adult patients admitted to ICUs who received insulin for stress hyperglycemia management." (PMID 38698018, 2024). "The study identified that 77% of the participants continued to receive antidiabetic therapy (oral hypoglycemic agents or insulin) or had persistent hyperglycemia at the end of 6 months." (PMID 39057114, 2024). "In conclusion, in patients with longstanding type 1 diabetes in whom residual beta cell function can be detected, several stimuli elicit a near-normal beta cell secretory response, except for the first phase insulin response to hyperglycemia." (PMID 38446636, 2024). "During hyperglycemia and fasting, rapid insulin pulses in older adults had lower amplitude than those of young adults." (PMID 39584020, 2024). "In patients with T2DM, glucagon levels are abnormally high during hyperglycemia, and lowering blood glucagon concentrations during hyperglycemia leads to reduced hepatic glucose output and reduced insulin requirements." (PMID 39598478, 2024). "In Cav2.3−/− murine models, fasting hyperglycemia has been observed not only due to impaired late-phase insulin secretion, but also to an altered glucagon release." (PMID 39201476, 2024). "This cohort study of pediatric patients with insulin-dependent diabetes compares hypoglycemia and hyperglycemia rates based on type of use of insulin pumps." (PMID 38324312, 2024). "Lastly, glucose transporter 2 (GLUT2), an insulin‐independent glucose transporter, significantly increased as possible feedback to hyperglycemia in aldh9a1b−/− zebrafish and in the tt‐DDE group." (PMID 38059818, 2024). "From the second trimester onwards, the fetal pancreas responds to hyperglycemia by secreting insulin, resulting in hyperinsulinemia." (PMID 38685068, 2024). "ALS-L1023 improved hyperglycaemia, hyperinsulinaemia, glucose and insulin tolerance, and normalised insulin-positive β-cell surface area in obese mice." (PMID 38675115, 2024). "Insulin therapy is employed as necessary to manage hyperglycemia as part of the preoperative optimization process." (PMID 38975526, 2024). "Aside from hyperglycemia, the insufficient response to insulin by its target organs, is also a significant pathological condition associated with IR." (PMID 38429305, 2024). "Increased insulin synthesis and release by the pancreas due to IR is necessary to achieve glucose homeostasis and prevent hyperglycemia." (PMID 38392069, 2024). "Crucially, the human body still secretes more insulin during the prediabetic state, and eventually, there is a reduction in insulin secretion that coincides with overt hyperglycemia and pancreatic failure." (PMID 38398039, 2024). "This feature contributes to preventing hyperglycaemia, which develops in insulin-resistant states, by increasing β cell mass and enhancing insulin secretion in response to increased insulin demand." (PMID 37945752, 2024). "Female global Alms1 KO mice were hyperglycaemic at both timepoints, and MSC-KO mice only at 19 weeks, with plasma insulin concentrations markedly increased whenever hyperglycemia was observed." (PMID 38583571, 2024). "These patients typically present with difficult-to-control hyperglycemia and require high-dose insulin therapy due to the severity of IR." (PMID 39398333, 2024). "WJMSCs-CM significantly ameliorated hyperglycemia, increased insulin and sex hormone levels, and improved sperm quality." (PMID 39391856, 2024).